STK39 (serine/threonine kinase 39)
Description:
Effector serine/threonine-protein kinase component of the WNK-SPAK/OSR1 kinase cascade, which is involved in various processes, such as ion transport, response to hypertonic stress and blood pressure. Specifically recognizes and binds proteins with a RFXV motif. Acts downstream of WNK kinases (WNK1, WNK2, WNK3 or WNK4): following activation by WNK kinases, catalyzes phosphorylation of ion cotransporters, such as SLC12A1/NKCC2, SLC12A2/NKCC1, SLC12A3/NCC, SLC12A5/KCC2 or SLC12A6/KCC3, regulating their activity. Mediates regulatory volume increase in response to hyperosmotic stress by catalyzing phosphorylation of ion cotransporters SLC12A1/NKCC2, SLC12A2/NKCC1 and SLC12A6/KCC3 downstream of WNK1 and WNK3 kinases. Phosphorylation of Na-K-Cl cotransporters SLC12A2/NKCC1 and SLC12A2/NKCC1 promote their activation and ion influx; simultaneously, phosphorylation of K-Cl cotransporters SLC12A5/KCC2 and SLC12A6/KCC3 inhibit their activity, blocking ion efflux. Acts as a regulator of NaCl reabsorption in the distal nephron by mediating phosphorylation and activation of the thiazide-sensitive Na-Cl cotransporter SLC12A3/NCC in distal convoluted tubule cells of kidney downstream of WNK4. Mediates the inhibition of SLC4A4, SLC26A6 as well as CFTR activities (By similarity). Phosphorylates RELT (By similarity).
Synonyms: SPAK; DCHT
Tractability: Small molecule: a high-quality ligand is known; it belongs to a druggable protein family. PROTAC: ubiquitination databases record sites on it; its protein half-life has been measured; a small molecule that binds it is known.
Target class: STE protein kinase STE20 family; Protein Kinase; Enzyme; Kinase; STE protein kinase FRAY subfamily; STE protein kinase group
Gene: Protein-coding gene on chromosome 2 (167,949,900 to 168,247,739, reverse strand). Ensembl gene ENSG00000198648.
Subcellular location: Cytoplasm; Nucleus
Subcellular location (Human Protein Atlas): Nucleoplasm; Cytosol; Vesicles
Gene Ontology:
Molecular function: ion channel regulator activity; protein binding; protein serine/threonine kinase activity; scaffold protein binding; transmembrane transporter binding; kinase activity; transporter activator activity; transporter inhibitor activity; transporter regulator activity; ATP binding; potassium channel inhibitor activity; protein kinase activity; protein kinase binding; protein serine kinase activity
Biological process: cell volume homeostasis; cellular hyperosmotic response; cellular response to chemokine; chemokine (C-X-C motif) ligand 12 signaling pathway; negative regulation of sodium ion transmembrane transport; negative regulation of transmembrane transport; peptidyl-serine phosphorylation; peptidyl-threonine phosphorylation; positive regulation of p38MAPK cascade; positive regulation of T cell chemotaxis; protein autophosphorylation; renal sodium ion absorption; signal transduction; cellular hypotonic response; intracellular signal transduction; maintenance of lens transparency; positive regulation of potassium ion import across plasma membrane; positive regulation of sodium ion import across plasma membrane; protein phosphorylation; regulation of monoatomic cation transmembrane transport; regulation of potassium ion transmembrane transport; cellular response to potassium ion; inflammatory response; intracellular chloride ion homeostasis; macrophage activation; and 5 more
Cellular component: cytosol; nucleoplasm; cell cortex; cytoplasm; apical plasma membrane; basolateral plasma membrane; cell body; membrane; nucleus
Genetic constraint (gnomAD): Loss-of-function variants: 15 observed, 60.61 expected, observed/expected ratio (o/e) 0.25, 90% interval 0.17 to 0.38. The upper end of that interval is the gene's LOEUF score, 0.38, which puts it in group 1 of 6, group 1 being the genes least tolerant of losing a copy. Missense variants: 402 observed, 561.62 expected, observed/expected ratio (o/e) 0.72, 90% interval 0.66 to 0.78. Synonymous variants: 196 observed, 195.28 expected, observed/expected ratio (o/e) 1, 90% interval 0.89 to 1.13.
Homologues: Orthologues: chimpanzee STK39 (99% identical), macaque STK39 (99% identical), rat Stk39 (97% identical), mouse Stk39 (97% identical), pig STK39 (97% identical), rabbit STK39 (96% identical), dog STK39 (93% identical), guinea pig STK39 (85% identical), tropical clawed frog stk39 (81% identical), zebrafish stk39 (74% identical), Drosophila melanogaster fray (56% identical), Caenorhabditis elegans gck-3 (53% identical). Paralogues in human: OXSR1 (72% identical), MAP4K4 (32% identical), TNIK (31% identical), MINK1 (30% identical), STK26 (29% identical), SLK (28% identical), MAP4K3 (28% identical), STK10 (27% identical), STK24 (27% identical), STK25 (27% identical), TAOK1 (27% identical), MAP4K5 (27% identical), and 23 more.
Diseases named in the same sentence as STK39 in open-access papers:
STK39 is named in the same sentence as 99 diseases in open-access papers, as found by Europe PMC text mining. Sharing a sentence is not in itself a finding about the gene and the disease. The quoted sentences say what the papers report.
Hypertension (43 papers, 2009 to 2026). The presence of chronic increased pressure in the systemic arterial system. "STK39 was identified as a potential hypertension susceptibility gene in a genome-wide association study (GWAS) conducted in the Amish population and subsequently validated in various non-Amish populations." (PMID 39859138, 2025). "The STK39 gene sequence is polymorphic, and 34 variants within the STK39 gene have been identified as being associated with hypertension." (PMID 39859138, 2025). "A study conducted in American Old Order Amish and two Swedish populations revealed that the functional polymorphism rs6749447 in STK39 was correlated with blood pressure (BP) and hypertension." (PMID 39859138, 2025). "An earlier whole-genome association study also identified STK39 as a hypertension susceptibility gene." (PMID 38674024, 2024). "The serine/threonine kinase 39 gene (STK39) was first identified as a hypertension-susceptibility gene by GWAS." (PMID 32128261, 2020). "Variants within STK39 are associated with susceptibility to essential hypertension, and constitutively active SPAK mice are hypertensive and hyperkalemic, similar to familial hyperkalemic hyperkalemia in humans." (PMID 32109341, 2020). "STK39 is an important kinase that has been associated with hypertension, Parkinson’s disease, and autism." (PMID 29490708, 2018). "Single nucleotide polymorphisms rs3754777 (STK39) and rs1468326 (WNK1) were associated with hypertension and BP in our multicenter Belgian case-control study, which supports the role of STK39 and WNK1 as potential hypertension susceptibility genes." (PMID 27082544, 2016). "We looked for an association between hypertension, BP, and genetic variants of STK39 and WNK1 in the BELHYPGEN case-control study, including predominantly severe hypertensive patients." (PMID 27082544, 2016). "Stk39 is involved in cation-chloride transport and polymorphisms in this gene are associated with the development of hypertension." (PMID 24886063, 2014). "The STK39 has been associated with hypertension, autism, and early-stage non-small-cell lung cancer." (PMID 24312176, 2013). "Since then, six publications covering 11 studies have been conducted to investigate the association between STK39 variants and hypertension." (PMID 23527223, 2013). "The meta-analysis showed a significant association of STK39 rs3754777 variant with hypertension (OR = 1.10, 95%CI = 1.06–1.15, p = 7.95×10−6)." (PMID 23527223, 2013). "Therefore, it is unsurprising that single nucleotide polymorphisms (SNPs) within STK39 were discovered to be associated with hypertension through the genome-wide association studies (GWASs)." (PMID 39859138, 2025). "STK39 was recognized as a hypertension risk factor through whole-genome association studies." (PMID 32602534, 2020). "Indeed, variations in the STK39 gene have been implicated in hypertension in the Amish population through genome-wide association, with the resulting non-coding mutations increasing the allelic expression of SPAK." (PMID 25009465, 2014). "The three reported STK39 SNPs associating with PD differ from the reported SNP for hypertension." (PMID 25009465, 2014). "Finally, genes and/or susceptibility loci on the long arm of chromosome 2 have been recently linked to blood pressure and hypertension by genome-wide association studies, such as STK39 at 2q24.3; PMS1 and MSTN, both at 2q32.2; DS2S2382 and DS2S338 at 2q35–q37." (PMID 22686481, 2012). "Single nucleotide polymorphisms (SNPs) at the STK39 locus were recently associated with hypertension by genome-wide association in an Amish population; in vitro data from transient transfection experiments using reporter constructs suggested that altered STK39 expression might mediate the effect." (PMID 20003416, 2009). "Our study extended the multifaceted role STK39 in human disease from that of a key regulator of hypertension to a key metastasis promoter." (PMID 34335956, 2021).
Hypertension (continued). "In addition, we could not address the effect of gene–gene/gene–environment interactions in this meta-analysis, though several papers have reported the effect of interaction between STK39 SNP and sex, BMI or hormone replacement therapy on susceptibility to hypertension." (PMID 23527223, 2013). "The aim of this meta-analysis was to assess the risk prediction of three promising SNPs, rs6749447, rs35929607 and rs3754777 in STK39, for primary hypertension, and none of these SNPs contributed to the significant risk of hypertension." (PMID 27142475, 2016). "The result confirms that rs3754777 SNP in STK39 is significantly associated with hypertension, and is independent of conventional environmental factors such as age, sex, body mass index (BMI) and lifestyle factors." (PMID 23527223, 2013). "In conclusion, the present meta-analysis confirmed the significant association between STK39 variants and hypertension in Europeans and East Asians but not in the Africans." (PMID 23527223, 2013). "In conclusion, our meta-analytical findings suggest that STK39 might not be a hypertension-susceptibility gene." (PMID 27142475, 2016). "Taken together, we through a comprehensive meta-analysis concluded that STK39 might not be a hypertension-susceptibility gene." (PMID 27142475, 2016). "Seven hundred seventy-nine Caucasian hypertensive patients (HYP) recruited in 6 academic centers from Belgium, and 906 normotensive (NT) controls were genotyped for 5 single nucleotide polymorphisms—rs3754777, rs6749447, rs35929607 (STK39), rs1468326, and rs765250 (WNK1)—using the Snapshot method." (PMID 27082544, 2016). "However, other large studies have not implicated STK39 in hypertension." (PMID 20003416, 2009).
breast cancer (15 papers, 2014 to 2025). A primary or metastatic malignant neoplasm involving the breast. "In breast cancer, STK39 is reported as an early antigen, and its expression was associated with poor prognosis." (PMID 37454130, 2023). "A recent report has identified the involvement of STK39 in breast cancer progression and metastasis." (PMID 37454130, 2023). "Of note, STK3 and STK39 activation were reported in HER2-positive breast cancer cell lines after anti-HER2 blockade, suggesting these roles in resistance to anti-HER2 therapy." (PMID 35338158, 2022). "By contrast, it is reported that STK39 was overexpressed in renal cell carcinoma, osteosarcoma and breast cancer cells, while the knockdown of STK39 inhibited proliferation, metastasis and EMT of these cancer cells." (PMID 34281492, 2021). "The expression of STK39 in breast cancer tissues is also significantly increased, and the inhibition of the expression of STK39 induced the suppression of the proliferation and invasiveness of breast cancer cells." (PMID 34519635, 2021). "To sum up, we found that CDKN2B-AS1 acts as a miR-122-5p sponge to regulate the STK39 expression, and promotes breast cancer progression." (PMID 34374638, 2021). "In our study, we first revealed that CDKN2B-AS1 acted as a miR-122-5p sponge to regulate the STK39 expression, and promoted breast cancer progression." (PMID 34374638, 2021). "To explore the functional role of STK39, we expressed STK39 in two luminal breast cancer cell lines, MCF7 and T-47D." (PMID 34335956, 2021). "To further assess the function of STK39 in breast cancer, we established clones with STK39 knockdown in MDA-MB-231 and MDA-MB-157 cells." (PMID 34335956, 2021). "Through a series of functional and mechanism experiments, we concluded that lncRNA CDKN2B-AS1 acts as a miR-122-5p sponge to regulate the STK39 expression, and promotes breast cancer progression." (PMID 34374638, 2021). "Taken together, these results clearly suggest that STK39 enhances breast cancer metastasis, in large part, in SNAI1-dependent manner." (PMID 34335956, 2021). "Overall, our data uncovers a novel mechanism for a STK39-SNAI1 axis in EMT and further underscores STK39 as a promising therapeutic target for breast cancer treatment." (PMID 34335956, 2021). "For instance, the therapeutic resistance of breast cancer is affected by down-regulated levels of STK39." (PMID 34281492, 2021). "For instance, in breast cancer, Li C reported that STK39 regulated by miR-299-5p promoted cell metastasis." (PMID 34374638, 2021). "Our data concluded that knockdown of CDKN2B-AS1 suppresses the progression of breast cancer by miR-122-5p/STK39 axis." (PMID 34374638, 2021). "We identified 6 autoantibodies that were present in mice prior to the development of mammary cancer: Pdhx, Otud6b, Stk39, Zpf238, Lgals8, and Vps35." (PMID 24886063, 2014). "CBX2 plays a role in epigenetic regulation and hematopoietic stem cell differentiation, whereas the STK32B gene is one of several serine/threonine kinases (STK32B, STK36, and STK39) with similar gene expression patterns in basal-like breast cancers." (PMID 24885002, 2014). "Furthermore, in mouse mammary tumors, vaccination with tumor antigens (Otud6b, Pdhx or Stk39) induced tumor-specific CD4+ and CD8+ T cells, along with tumor-specific IFN-g T cell and CD8+ T cell responses." (PMID 40651961, 2025). "Finally, it has been shown that CDKN2B-AS1 regulates the expression of STK39 by acting as a sponge for hsa-mir-122-5p, thereby promoting breast cancer progression, and hsa-mir-122-5p modulates STK39 expression to regulate the impact of sh-CDKN2B-AS1." (PMID 37987362, 2023). "Therefore, our study not only uncovers a role for STK39 in breast cancer progression but also provides new insights into the regulation of SNAI1." (PMID 34335956, 2021). "In breast cancer, there was a relevance between the decreased STK39 and treatment resistance." (PMID 34281492, 2021).
breast cancer (continued). "We then treated several breast cancer cells with the STK39 inhibitor STOCK2S 26016 (STO)." (PMID 34335956, 2021). "STK39 is a potential target of miR-122-5p and an upward trend was discovered in breast cancer." (PMID 34374638, 2021). "Our data suggest that STK39 inhibition sensitizes breast cancer cells to PTX." (PMID 34335956, 2021). "In conclusion, these data support our hypothesis that lncRNA CDKN2B-AS1 acts as a miR-122-5p sponge to regulate the STK39 expression, and promotes breast cancer progression." (PMID 34374638, 2021). "Meanwhile, many studies reported that STK39 accelerated the development of breast cancer." (PMID 34374638, 2021). "More importantly, several reports have revealed that STK39 promoted progression of breast cancer." (PMID 34374638, 2021). "Hence, STK39 could regulate the development of breast cancer and reducing STK39 expression receded the malignancy of breast cancer." (PMID 34374638, 2021). "Also, STK39 expression correlates with poor survival of breast cancer patients." (PMID 34335956, 2021). "Considering that epigenetic silencing like methylation has been reported to be one of the most effective processes for the regulation of STK39 expression, it is reasonable to speculate that such probe targeting STK39 may also distinguish luminal subtypes from other breast cancer subtypes." (PMID 31480430, 2019). "Our studies clearly showed that STK39 controls EMT by stabilizing the CDH1 repressors of SNAI1 and is crucial for migration in breast cancer." (PMID 34335956, 2021). "Notably, STK39 protein levels did not correlate with the SNAI1 protein expression in breast cancer cell lines and breast cancer tissues (data not shown) because the activity of STK39 need to be activated." (PMID 34335956, 2021).
hepatocellular carcinoma (10 papers, 2020 to 2025). A malignant tumor that arises from hepatocytes. "Certainly, the expression of wnk1a, stk39, osr1a, and osr1b is upregulated when hepatocytes increase proliferation and display histopathological changes as hepatocellular carcinoma." (PMID 36292952, 2022). "Previous studies have indicated that STK39 accelerates the development of most cancer, such as hepatocellular carcinoma, osteosarcoma and NSCLC." (PMID 34374638, 2021). "Second, it is conceivable that knockdown of STK39 suppressed the proliferation and invasiveness of hepatocellular carcinoma cells by repressing the phosphorylation of p38." (PMID 34519635, 2021). "Obviously, the expression of wnk1a, osr1b, and stk39 is upregulated, while pppsr1ba and ppp2r1bb are downregulated in zebrafish when hepatocytes increase proliferation and display histopathological changes as hepatocellular carcinoma." (PMID 36292952, 2022). "For instance, the increased expression of STK39 in hepatocellular carcinoma (HCC) contributes to a decreased probability of patient survival." (PMID 37627077, 2023). "In this study, we compared STK39 expression in liver hepatocellular carcinoma tissues, normal tissues, multiple HCC cell lines and normal HHL-5 hepatocytes." (PMID 34281492, 2021). "Mechanistically, it was revealed that STK39 bound with PLK1 and then activated MAPK signaling pathway, which consequently promoted tumor proliferation and aggression in hepatocellular carcinoma." (PMID 37031178, 2023). "Because WNK1 activates OSR1/SPAK, if OSR1 or STK39 are involved in tumor-induced angiogenesis, they are supposed to be upregulated from 2 dpi to 3 dpi, so these results indicate that WNK1 and OSR1 in hepatoma cells are involved in tumor-induced angiogenesis." (PMID 36292952, 2022). "Bioinformatics analysis showed that Serine/threonine kinase 39 (STK39), which was testified to play an important role in human cancers, may be a hub gene in diagnosing hepatocellular carcinoma (HCC)." (PMID 34281492, 2021).
Hypokalemia (10 papers, 2015 to 2025). An abnormally decreased potassium concentration in the blood. "During hypokalemia, the WNKs activate the kinases STE20/SPS1-related proline-alanine-rich protein kinase (SPAK, also known as STK39) and OSR1 (OXSR1), which phosphorylate NCC directly." (PMID 40493421, 2025).